PLCD3 (phospholipase C delta 3)
Description:
Hydrolyzes the phosphatidylinositol 4,5-bisphosphate (PIP2) to generate 2 second messenger molecules diacylglycerol (DAG) and inositol 1,4,5-trisphosphate (IP3). DAG mediates the activation of protein kinase C (PKC), while IP3 releases Ca(2+) from intracellular stores. Essential for trophoblast and placental development. May participate in cytokinesis by hydrolyzing PIP2 at the cleavage furrow. Regulates neurite outgrowth through the inhibition of RhoA/Rho kinase signaling (By similarity).
Synonyms: PLC-delta-3
Tractability: Antibody: its Gene Ontology location is reachable by antibodies, with high confidence; UniProt places it where antibodies can reach, with medium confidence; the Human Protein Atlas places it where antibodies can reach. PROTAC: ubiquitination databases record sites on it.
Gene: Protein-coding gene on chromosome 17 (45,108,959 to 45,133,354, reverse strand). Ensembl gene ENSG00000161714.
Subcellular location: Cell membrane; Cytoplasm; Cleavage furrow
Subcellular location (Human Protein Atlas): Plasma membrane
Pathways (Reactome):
Metabolism: Synthesis of IP3 and IP4 in the cytosol
Gene Ontology:
Molecular function: phosphatidylinositol-4,5-bisphosphate phospholipase C activity; phosphoric diester hydrolase activity
Biological process: intracellular signal transduction; lipid metabolic process; signal transduction
Cellular component: cleavage furrow; cytoplasmic side of plasma membrane; plasma membrane; cytoplasm
Genetic constraint (gnomAD): Loss-of-function variants: 63 observed, 66.23 expected, observed/expected ratio (o/e) 0.95, 90% interval 0.78 to 1.17. The synonymous counts are far from expectation, so gnomAD's model fits this gene poorly and the ratio says little. Missense variants: 1,023 observed, 975.87 expected, observed/expected ratio (o/e) 1.05, 90% interval 1 to 1.1. Synonymous variants: 478 observed, 402.46 expected, observed/expected ratio (o/e) 1.19, 90% interval 1.1 to 1.28.
Homologues: Orthologues: chimpanzee PLCD3 (99% identical), macaque PLCD3 (98% identical), pig PLCD3 (91% identical), dog PLCD3 (90% identical), rabbit PLCD3 (90% identical), mouse Plcd3 (88% identical), rat Plcd3 (87% identical), guinea pig PLCD3 (80% identical), tropical clawed frog plcd3 (58% identical), zebrafish plcd3a (51% identical), zebrafish plcd3b (49% identical), Caenorhabditis elegans plc-4 (33% identical), and 4 more. Paralogues in human: PLCD1 (48% identical), PLCD4 (46% identical), PLCH2 (35% identical), PLCH1 (35% identical), PLCL2 (34% identical), PLCL1 (33% identical), PLCG1 (32% identical), PLCB2 (31% identical), PLCE1 (30% identical), PLCB3 (30% identical), PLCZ1 (30% identical), PLCB4 (30% identical), and 2 more.
Diseases named in the same sentence as PLCD3 in open-access papers:
PLCD3 is named in the same sentence as 33 diseases in open-access papers, as found by Europe PMC text mining. Sharing a sentence is not in itself a finding about the gene and the disease. The quoted sentences say what the papers report.
Hypertension (4 papers, 2012 to 2025). The presence of chronic increased pressure in the systemic arterial system. "In humans, down-regulation of PLCD3 in the right ventricular outflow tract may be associated with idiopathic ventricular arrhythmias and a genomic locus associated with hypertension has been mapped near the PLCD3 locus." (PMID 22723964, 2012). "PLCD3 was involved in hypertension, cutaneous melanoma, and breast adenocarcinoma by Open Targets Platform." (PMID 37007130, 2023).
nasopharyngeal carcinoma (3 papers, 2020 to 2025). A carcinoma arising from the nasopharyngeal epithelium. "Of the upregulated DEGs, PLCD3 was previously reported to be implicated in the proliferation, migration, and invasion of nasopharyngeal carcinoma cells." (PMID 40032892, 2025). "Taken together, it can be concluded that PLCD3 plays a role as an oncogene in nasopharyngeal cancer, breast cancer, and pancreatic cancer." (PMID 31808619, 2020). "PLCD3 is involved in the proliferation, migration, and invasion of nasopharyngeal carcinoma." (PMID 37007130, 2023).
osteosarcoma (2 papers, 2023 to 2025). A usually aggressive malignant bone-forming mesenchymal neoplasm, predominantly affecting adolescents and young adults. "PLCD3 could facilitate the proliferation and migration of osteosarcoma." (PMID 37007130, 2023). "As PLCD3 was not studied in osteosarcoma, the in vitro validation was performed on PLCD3." (PMID 37007130, 2023).
thyroid cancer (2 papers, 2023). "PLCD3 inhibits apoptosis and promotes thyroid cancer’s proliferation, migration, and invasion via the Hippo pathway." (PMID 37007130, 2023).
alcoholism (1 paper, 2020). "Our investigation also suggests that overexpression of PLCD3 is associated with a history of alcoholism, which is partially explained by the role of alcohol in pancreatic cancer." (PMID 31808619, 2020). "In the stratified survival analysis, PLCD3 expression was found to be associated with the OS of PDAC patients who were >60 years of age, female, had a history of alcoholism, a low histological grade, had undergone radiation therapy, or R0 residual resection." (PMID 31808619, 2020). "In PDAC patients, PLCD3 is overexpressed in certain groups of people with a history of alcoholism (P = .032)." (PMID 31808619, 2020). "PLCD3 was also found to be overexpressed in patients with a history of alcoholism (P = .032)." (PMID 31808619, 2020). "Moreover, we also discovered that PLCD3 is highly expressed in PDAC patients with a history of alcoholism." (PMID 31808619, 2020). "However, the stratification analysis found that PLCD3 is associated with OS only in early stage PDAC patients who are >60 years of age, female, have a history of alcoholism, a low histological grade, have undergone radiation therapy, or R0 residual resection." (PMID 31808619, 2020). "We also discovered that PDAC patients with a history of alcoholism had higher levels of PLCD3 than those without a history of alcoholism." (PMID 31808619, 2020).
alopecia (1 paper, 2012). Hair loss usually from the scalp. "Inactivation of Plcd1 alone causes loss of hair (alopecia), whereas inactivation of Plcd3 alone has no apparent phenotypic effect." (PMID 22723964, 2012).
atherosclerosis (1 paper, 2024). A disease characterized by the build-up of fatty material and calcium deposition in the arterial wall resulting in partial or complete occlusion of the arterial lumen. "PLCD3 is one of three positional candidates in the 17q21 region, where it plays an important role in the phosphoinositide (PI) cycle, which can influence vascular tone and cell proliferation, ultimately leading to atherosclerosis." (PMID 38305998, 2024).
breast tumour (1 paper, 2024). "PLCD3 is also involved in the proliferation and migration of breast tumour cells." (PMID 38305998, 2024).
cardiomyopathy (1 paper, 2014). A disease of the heart muscle or myocardium proper. "In this study, we demonstrated that the simultaneous loss of PLCδ1 and PLCδ3 induces cardiac fibrosis, hypertrophy of cardiomyocytes, so-called pathological remodeling, and cardiomyopathy." (PMID 24810051, 2014).
colon cancer (1 paper, 2024). "The knockdown of PLCD3 in colon cancer impairs the development of microvillous structures and, as a result, promotes colon cancer development." (PMID 38305998, 2024).
esophageal squamous cell carcinoma (1 paper, 2023). Esophageal squamous cell carcinoma (ESCC) is a type of esophageal carcinoma (EC) that can affect any part of the esophagus, but is usually located in the upper or middle third. "PLCD3 promotes malignant cell behaviors in esophageal squamous cell carcinoma via the PI3K/AKT/P21 signaling and could serve as a potential target for ESCC treatment." (PMID 37773107, 2023). "However, little is known about the role of PLCD3 in esophageal squamous cell carcinoma (ESCC)." (PMID 37773107, 2023).
gastric cancer (1 paper, 2024). A primary or metastatic malignant neoplasm involving the stomach. "Knockdown of PLCD3 inhibited gastric cancer migration and invasion in both wound healing and transforaminal migration and invasion assays." (PMID 38305998, 2024). "PLCD3 has a crucial function in controlling gastric cancer migratory ability, as revealed by wound healing and transwell assays." (PMID 38305998, 2024). "This study provides an important target for future targeted therapy with novel molecules by emphasizing the significant role PLCD3 plays in the development of gastric cancer." (PMID 38305998, 2024). "We conducted protein immunoblotting experiments in order to provide further evidence of the role that PLCD3 plays in promoting the migration and invasion of gastric cancer." (PMID 38305998, 2024). "As a final step in our study, we investigated the combined effects of PLCD3 and its closely related pathways on the biological functions of gastric cancer." (PMID 38305998, 2024). "The purpose of this study was to investigate the expression and mechanism of action of PLCD3 in connection to gastric cancer." (PMID 38305998, 2024). "According to these findings, PLCD3 may be involved in the proliferation, invasion, and migration of gastric cancer." (PMID 38305998, 2024). "In conclusion, PLCD3 inhibits apoptosis and promotes proliferation, invasion, and migration, which indicated that PLCD3 might serve as a therapeutic target for gastric cancer." (PMID 38305998, 2024). "PLCD3 expression in gastric cancer and its predictive value were investigated in this study." (PMID 38305998, 2024).
Headache (1 paper, 2022). Cephalgia, or pain sensed in various parts of the head, not confined to the area of distribution of any nerve. "The second strongest association was at chromosome 17, rs4986170 (pmeta = 5.20 × 10−10) for headache and TSH, located near PLCD3." (PMID 36672757, 2022). "Of the genes at these loci, six (FAF1, TMX2-CTNND1, AARSD1, PLCD3, ZNF652, and C20orf203; headache-TSH) and six (HMGB1P45, RPL30P1, ZNF462, TMX2-CTNND1, ITPK1, SECISBP2L; headache-fT4) were significant in our gene-based analysis (pFisher’s combined p-value < 2.09 × 10−6)." (PMID 36672757, 2022).
heart failure (1 paper, 2014). Inability of the heart to pump blood at an adequate rate to meet tissue metabolic requirements. "The findings of this study suggest that PLCδ1 and PLCδ3 are possible therapeutic targets for DCM and cardiac remodeling that leads to heart failure." (PMID 24810051, 2014). "Future work will determine whether the expression and/or activity of PLCδ1 and PLCδ3 in patients with DCM and/or heart failure are decreased." (PMID 24810051, 2014).
lung carcinoma (1 paper, 2022). "Among the 363 up-regulated genes, 32 are prognostic markers in lung cancer, all of unfavorable prognosis, including LRP8, NUP62CL, FSCN1, PLCD3 or HMGA1." (PMID 36544755, 2022).
metastasis (1 paper, 2023). The spread or migration of cancer cells from one part of the body (where they first appeared) to another. "We found significant differences between high PLCD3 expression in Pathologic stage and Lymphatic metastasis (p = 0.03, p = 0.01, respectively)." (PMID 37773107, 2023).
tumor (6 papers, 2020 to 2025). "The results showed that PLCD3 expression was associated with age (P = 0.007), tumor size (P = 0.008), Laure type (P = 0.010), and TNM stage (P = 0.025)." (PMID 38305998, 2024). "Relatively, PLCD3 level is modulated by circ_0003747/miR-338-3p axis, and suppressing PLCD3 expression reduces tumor size and growth." (PMID 40069775, 2025). "Phospholipase C Delta 3 (PLCD3) is verified as an oncogene in TC and the PLCD3 level is closely related to the tumor progression through hippo pathway probably and can serve as an auxiliary clinical diagnostic tool or a therapeutic target." (PMID 40069775, 2025). "In N87 and HGC-27 cells, the silencing of PLCD3 using small interfering RNA effectively induced apoptosis and inhibited tumor cell proliferation, invasion, and migration." (PMID 38305998, 2024). "The tumor-promoting activity of PLCD3 was investigated by in vitro tests since it is a crucial gene in the CRP score." (PMID 37007130, 2023). "The results showed that PLCD3 knockdown inhibited tumor growth, that is, a significant decrease in tumor volume and weight." (PMID 37773107, 2023). "In this study, we found that patients with high expression of PLCD3 have shorter overall survival and higher levels of PLCD3 expression in tumor tissue, which indicates that PLCD3 plays a role as an oncogene in PDAC." (PMID 31808619, 2020). "In our investigation, PLCD1 and PLCD3 were found to be highly expressed in PAAD tumor tissue, compared with normal tissue." (PMID 31808619, 2020). "In our investigation, PLCD1 and PLCD3 were found to be high expressed in PAAD tumor tissue compared with normal tissue." (PMID 31808619, 2020). "In addition, the expression of PLCD3 in tumor tissues was higher when compared to the expression in normal tissues in the TCGA database." (PMID 38305998, 2024). "Therefore, We explored whether PLCD3 could activate the PI3K/AKT pathway to promote tumor development." (PMID 37773107, 2023). "PLCD3 promotes the development of ESCC cells by regulating malignant behaviors such as proliferation, migration, and invasion, suggesting the tumor-promoting role of PLCD3 in ESCC." (PMID 37773107, 2023). "Using univariate regression analysis, we found the following factors to influence OS (P > 0.05): age, tumor size, Lauren type, TNM stage (stages I and II vs. stages III and IV), histological grade (stages I vs. II vs. III), and PLCD3 expression (low vs. high) (P > 0.05)." (PMID 38305998, 2024). "Additionally, high PLCD3 levels are correlated with TNM stage and tumor size." (PMID 38305998, 2024).
cancer (5 papers, 2020 to 2023). A tumor composed of atypical neoplastic, often pleomorphic cells that invade other tissues. "PLCD3 positively correlated with macrophages and negatively correlated with T cells in most cancers by TIMER." (PMID 37007130, 2023). "Phospholipase C Delta 3 (PLCD3) is a member of phospholipase C(PLC) Protein and PLCD3 protein plays a prominent role in many cancers." (PMID 37773107, 2023). "BTBD10 (43%), PLCD3 (27%), and RFX3 (24%) were frequently mutated in pan-cancer." (PMID 37007130, 2023). "However, despite evidence of the oncosuppressor function of PLCδ1, there is still little knowledge about the activity of PLCδ3, whose activation in cancer cells is still poorly defined and controversial." (PMID 35159043, 2022).
PLCD3 also shares sentences with these, for which no sentence is quoted: breast carcinoma (2 papers); adenoma (1); brain disorder (1); breast adenocarcinoma (1); cardiac ischemia (1); cutaneous melanoma (1); depression (1); esophageal cancer (1); fibrosis (1); infection (1); metastatic disease (1); pancreatic cancer (1); pancreatic ductal carcinoma (1); schizophrenia (1); Ventricular arrhythmia (1).